RNU6-462P (RNA, U6 small nuclear 462, pseudogene)
Gene: Small nuclear RNA gene on chromosome 4 (101,723,876 to 101,723,980, forward strand). Ensembl gene ENSG00000199529.
Homologues: Orthologues: chimpanzee U6 (93% identical), macaque U6 (64% identical), rat LOC120099049 (59% identical). Paralogues in human: RNU6-144P (79% identical), RNU6-1029P (78% identical), RNU6-20P (78% identical), RNU6-1011P (77% identical), RNU6-16P (77% identical), RNU6-333P (77% identical), RNU6-35P (77% identical), RNU6-38P (77% identical), RNU6-434P (77% identical), RNU6-49P (77% identical), RNU6-737P (77% identical), RNU6-73P (77% identical), and 1284 more.